S100A7 (S100 calcium binding protein A7)
Synonyms: PSOR1; S100A7C
Tractability: Small molecule: a structure with a bound ligand is known; it has a binding pocket of medium quality. Antibody: UniProt places it where antibodies can reach, with high confidence; its Gene Ontology location is reachable by antibodies, with high confidence.
Gene: Protein-coding gene on chromosome 1 (153,457,744 to 153,460,651, reverse strand). Ensembl gene ENSG00000143556.
Subcellular location: Cytoplasm; Secreted
Subcellular location (Human Protein Atlas): Cytosol; Predicted to be secreted
Pathways (Reactome):
Immune System: Metal sequestration by antimicrobial proteins; Neutrophil degranulation
Gene Ontology:
Molecular function: calcium ion binding; protein binding; RAGE receptor binding; zinc ion sequestering activity; calcium-dependent protein binding; zinc ion binding; transition metal ion binding
Biological process: antimicrobial humoral immune response mediated by antimicrobial peptide; positive regulation of ERK1 and ERK2 cascade; positive regulation of granulocyte chemotaxis; positive regulation of monocyte chemotaxis; positive regulation of T cell chemotaxis; response to lipopolysaccharide; response to reactive oxygen species; angiogenesis; endothelial cell migration; epidermis development; keratinocyte differentiation
Cellular component: cytoplasm; cytosol; endoplasmic reticulum; extracellular matrix; extracellular region; nucleus; azurophil granule lumen; focal adhesion
Genetic constraint (gnomAD): Loss-of-function variants: 2 observed, 3.23 expected, observed/expected ratio (o/e) 0.62, 90% interval 0.25 to 1.68. That is too few expected variants to judge how well the gene tolerates losing a copy. Missense variants: 112 observed, 106.13 expected, observed/expected ratio (o/e) 1.06, 90% interval 0.9 to 1.24. Synonymous variants: 44 observed, 38.56 expected, observed/expected ratio (o/e) 1.14, 90% interval 0.89 to 1.47.
Homologues: Orthologues: chimpanzee S100A7 (96% identical), tropical clawed frog s100a11 (24% identical), zebrafish s100t (23% identical), zebrafish s100a10a (22% identical), zebrafish s100s (21% identical). Paralogues in human: S100A7A (94% identical), S100A11 (29% identical), S100A10 (25% identical), S100G (25% identical), S100Z (25% identical), S100A16 (24% identical), S100A9 (24% identical), S100B (23% identical), S100A2 (22% identical), S100A4 (22% identical), S100A5 (22% identical), SNTN (22% identical), and 9 more.
Diseases named in the same sentence as S100A7 in open-access papers:
S100A7 is named in the same sentence as 139 diseases in open-access papers, as found by Europe PMC text mining. Sharing a sentence is not in itself a finding about the gene and the disease. The quoted sentences say what the papers report.
psoriasis (105 papers, 2010 to 2025). An autoimmune condition characterized by red, well-delineated plaques with silvery scales that are usually on the extensor surfaces and scalp. "Decision curve analysis (DCA) demonstrated that the nomogram provided superior clinical utility in predicting psoriasis occurrence probability at a high-risk threshold of 0–1, compared to individual curves for S100A7, SERPINB13, and PLBD1." (PMID 38699235, 2024). "Because of the important role of S100A7 in amplifying inflammatory process in psoriatic lesions, S100A7 becomes a potential diagnostic and therapeutic target for psoriasis." (PMID 37346040, 2023). "The altered expression of S100A7 is associated with keratinocyte differentiation and poor prognosis of psoriasis." (PMID 37346040, 2023). "S100A7 can also be produced by circulating cells, possibly contributing to systemic inflammation and psoriasis-associated comorbidities." (PMID 37346040, 2023). "BD‐2 is a biomarker of IL‐17A‐driven pathology in psoriasis and S100A7 is associated with the severity of HS disease (Hurley staging), making these mediators useful surrogate markers of downstream IL‐17 activity." (PMID 35638561, 2022). "We confirmed that the low expression level of IκBζ via SKSI-0412 administration caused a decrease in HBD-2 and S100A7 levels, which are psoriasis-associated genes." (PMID 34445513, 2021). "CTD associates S100A7 with psoriasis, drug-induced liver injury, nervous system malformation, inflammation, and congenital heart defects." (PMID 33546175, 2021). "Inflammatory skin conditions like psoriasis are linked to elevated levels of both IL-1a and S100A7 (also known as psoriasin) and an increased signalling axis composed of NF-κB/p38MAPK/Caspase-1/IL-1a, which regulates S100A7." (PMID 34203393, 2021). "UCB-MNC-sEV treatment significantly reduced the expression of psoriasis-associated molecules, including IL-6 and IL-8, as well as antimicrobial peptides S100A7 and DEFB4, thereby supporting its therapeutic potential for this disease." (PMID 34575956, 2021). "Our data confirmed several proteins already known to be associated with psoriasis, including S100A7, S100A9, beta-defensin 3(DEFB103A), Elafin (PI3), serine protease inhibitors B3, and B4." (PMID 32849499, 2020). "Increasing evidence supports an association of S100A7 with several inflammatory skin diseases, including psoriasis and atopic dermatitis." (PMID 29379499, 2017). "S100A7 is over-expressed in hyperproliferative skin disease-psoriasis and is also associated with the early stages or invasion of certain cancers." (PMID 23228205, 2012). "Immunohistochemical, western blot, and multiplex analysis showed that the TLR activation induced the expression of psoriasis associated markers like S100A7, p-STAT3, CXCL-1, IL-8, IL-1α, S100A9, and IL-23 in the wild type but not in the TLR KO epidermis models." (PMID 40995100, 2025). "In contrast to psoriasis-associated cytokines, however, Th2-associated cytokines, such as IL-4 and histamine, may hinder the expression of S100A7 in the skin." (PMID 38606161, 2024). "Human S100A7 expression is associated with epidermal thickness in psoriasis." (PMID 28060905, 2017). "S100A7 is a potent chemotaxin that has thoroughly engaged in a pro-inflammatory feedback loop which is important in the pathogenic process of human disorders including psoriasis, atopic dermatitis and breast cancer." (PMID 26633653, 2015). "The skin model with normal keratinocytes showed a strong expression of the psoriasis marker S100A7 if activated CD4+ T cells were integrated." (PMID 40678130, 2025). "This pre-psoriatic like phenotype was characterized by higher sensitivity to cytokine treatment and an elevated basal expression of the psoriasis marker S100A7 in STAT3 overexpressing full-thickness skin models." (PMID 40678130, 2025). "STAT3 overexpressing skin models without psoriatic stimuli resembled histologically normal skin but expressed abnormal high levels of the psoriasis marker S100A7." (PMID 40678130, 2025).
psoriasis (continued). "In the full-thickness skin models STAT3 overexpression by its own was sufficient to induce enhanced expression of the psoriasis marker S100A7." (PMID 40678130, 2025). "Concerning S100A7, a biomarker for psoriasis (playing a role in the inflammation and abnormal skin growth), no significant change in expression or secretion was observed regardless of treatment." (PMID 41226468, 2025). "We demonstrated that treatment of in vitro epidermis models with the TLR2 agonist Pam2CSK4 and the TLR3 agonist poly(I:C) induced the expression of the psoriasis marker S100A7." (PMID 40995100, 2025). "Epidermis models based on Ker-CT_STAT3 responded to IL-22 with stronger expression of the psoriasis marker S100A7, with more pronounced acanthosis and with an increased metabolic activity compared to the wild-type cell line Ker-CT." (PMID 40678130, 2025). "In psoriasis, S100A7, S100A8, S100A9, S100A12, and S100A5, defined as “antimicrobial peptides”, are the main S100 family members involved." (PMID 38255845, 2024). "Proinflammatory cytokines IL-1α, TNF-α, IL-1β and S100A7 have been reported to be up-regulated in psoriatic skins and they are involved in the psoriasis pathogenesis." (PMID 38393364, 2024). "Among them, S100A7 is overexpressed in the damaged skin of psoriasis patients but tends to decrease in serum with increasing disease severity." (PMID 38255845, 2024). "Previous studies showed that the S100A7 mouse model of psoriasis exhibited lesions that were characterized by leukocyte inflammation." (PMID 38434138, 2024). "In psoriasis, for instance, S100A7 was found to induce the expression of mature interleukin-1α via the RAGE-p38 MAPK-calpain 1 pathway, which triggers an inflammatory response in the body." (PMID 38255845, 2024). "In our study, the strong increase of IL-1α, TNF-α, IL-1β and S100A7 was observed in psoriasis-like lesions." (PMID 38393364, 2024). "Various treatments, including calcipotriol, a vitamin D analog, and narrow-band UVB phototherapy, have been found to reduce S100A7 expression and interfere with the inflammatory loop, potentially leading to improved psoriasis outcomes." (PMID 38699235, 2024). "In 2013, it started with a proteomics approach on keratome skin biopsies of psoriasis patients to discover alterations of psoriasis-related proteins S100A7, FABP5 and new potential biomarkers." (PMID 37175722, 2023). "As the signal pathway for the induction of S100A7 mediated by IL-17, IκBζ is an essential regulatory factor in the pathogenesis of psoriasis through IL-17A and IL-17F-mediated actions." (PMID 37891988, 2023). "S100A7, also called psoriasin, was first found as a protein overexpressed in psoriasis-involved skin and later identified as a biomarker of psoriasis-involved skin." (PMID 37346040, 2023). "To examine the anti-inflammatory effect of AOA on psoriasis, we observed changes in the expression of antimicrobial peptides, such as defensin β 4 (Defb4), lipocalin 2 (Lcn2), S100a7, and S100a9, which are known to amplify local inflammatory processes." (PMID 37649889, 2023). "Among them, the expression of IL17A is predominant in psoriasis skin lesions, and IL-17 increases the secretion of antimicrobial peptides (Defb4, Lcn2, S100a7, and S100a9) by keratinocytes." (PMID 37649889, 2023). "Peripheral blood mononuclear cells in patients with psoriasis produce S100A7 which increases the production of inflammatory cytokines such as IL-1β, IL-6, IL-8, and TNF-β." (PMID 37891988, 2023). "In our study, S100A7, S100A8 and S100A9 were significantly involved in the IL-17A pathway, which is strongly implicated in psoriasis pathogenesis." (PMID 36483564, 2022). "Psoriasin, also known as S100a7, is a psoriasis‐specific antimicrobial peptides (AMP) and was upregulated in the IMQ‐induced mouse epidermis." (PMID 35716036, 2022).
psoriasis (continued). "IL-17, the major effector cytokine in psoriasis, acts alone or synergistically with TNF-α to induce the expression and release of many psoriasis-related proteins from keratinocytes, such as β-defensin 4 and S100A7." (PMID 35884790, 2022). "S100A7 (Psoriasin), which is first identified in the epithelial cells of human psoriasis skin, is one of the AMP with a strong antimicrobial activity, especially against Escherichia coli in humans and bovine." (PMID 35498722, 2022). "S100A7 is an antimicrobial peptide that is stored in differentiated keratinocytes and S100A7 was significantly elevated in psoriasis patients." (PMID 35075118, 2022). "S100A7 is highly expressed in psoriasis and cPLA2 inhibitors are considered as potent anti-psoriasis agents." (PMID 35135586, 2022). "S100A7, an antimicrobial peptide, is also considered an inflammation-related protein, which was first found in patients with psoriasis in 1991; subsequently, more and more studies have proved that S100A7 plays an essential role in innate immunity." (PMID 36428305, 2022). "IκBζ, a mediator of IL17-A-induced transcriptome activity, is known as a key regulator of specific psoriasis-associated genes that include DEFB4, S100A7, and IL-16." (PMID 34445513, 2021). "The decrease in IκBζ expression due to SKSI-0412 causes decreased nuclear translocation, which subsequently causes decreased expression of the psoriasis-associated genes (DEFB4 and S100A7) in IL-17A-induced keratinocytes." (PMID 34445513, 2021). "Psoriasis-related genes in HaCaT cells, such as S100A7, S100A8, and S100A9, were downregulated by miR-193b-3p overexpression in the presence or absence of M5 treatment." (PMID 34667159, 2021). "Some of these transcripts encode proteins that have been proposed as potential biomarkers for intra-amniotic infection or inflammation in women with preterm labor, such as ENSECAG00000008686 (psoriasis; S100A7) and ENSECAG00000010615 (calgranulin B; S100A9)." (PMID 34238364, 2021). "Expression of S100A7 and Keratin‐16, two epidermal markers upregulated in psoriasis lesions, was strongly induced in the suprabasal layers of the epidermis in the InflammaSkin® model, suggesting the presence of Th17‐mediated epidermal inflammation." (PMID 32737987, 2020). "In particular, the host employs S100 family proteins, such as S100A7 protein psoriasis secreted by keratinocytes and S100A8/S100A9 dimer calprotectin secreted by neutrophil granulocytes to sequester zinc locally and extracellularly." (PMID 33028391, 2020). "S100A7 (psoriasin) is reported as a potent and selective chemotactic inflammatory protein for T cells and neutrophils in psoriasis." (PMID 33050592, 2020). "S100A7, S100A8 and S100A9, calcium-binding proteins, are located in the psoriasis susceptibility locus 4 and are highly expressed at the epidermis of psoriasis skin lesions." (PMID 32194991, 2020). "S100A7, another antimicrobial protein, has been reported to be significantly elevated in patients with psoriasis and atherosclerosis." (PMID 31766659, 2019). "The expression of S100A15 (Koebnerisin) and S100A7 (Psoriasin) are increased in circulating peripheral blood mononuclear cells (PBMCs) in patients with psoriasis." (PMID 30865695, 2019). "Nine of the top 50 upregulated DEGs in HS were genes known to be upregulated in psoriasis (PS), including AMPs S100A7, A9, DEFB4, as well as SERPINB3 AND B4." (PMID 30265680, 2018). "The S100A7 psoriasis protein has been discovered and identified in psoriatic plaques and is overexpressed in the skin of patients with psoriasis." (PMID 29156622, 2017). "Such is the case of gene S100A7 in psoriasis, which first raised interest as a highly expressed gene in psoriatic skin." (PMID 29020950, 2017). "The S100A7 expression was found to be upregulated in the lesioned epidermis of atopic dermatitis and psoriasis, which is where this keratinocyte-derived chemoattractant engaged in the pro-inflammatory feedback loop." (PMID 26633653, 2015).
psoriasis (continued). "IL-17A, a crucial player in pathogenesis of psoriasis, is principal inducer of both proteins which acts synergistically with other propsoriatic cytokines to induce S100A7 and S100A15." (PMID 24901012, 2014). "Psoriasin, also known as S100A7, is a member of the S100 gene family that was identified as a 11.4 kDa protein induced in the epidermis isolated from psoriasis." (PMID 23228205, 2012). "Cytokeratin 16 (CK16) and S100A7, are common psoriasis marker also used in the clinic." (PMID 40678130, 2025). "In addition to S100A7 and p-STAT3, the expression profiles of further psoriasis associated secreted immune mediators of the wild type and TLR2 or TLR3 KO epidermis models after stimulation with Pam2CSK4 or poly(I:C) were investigated with a multiplex assay." (PMID 40995100, 2025). "The MSX2P1–miR-6731-5p–S100A7 pathway may represent a promising therapeutic target for future psoriasis treatment modalities." (PMID 40725772, 2025). "Additionally, si-Yap1 significantly decreased the expression of psoriasis-related genes, including S100a7, S100a8, and S100a9." (PMID 40108109, 2025). "Bimekizumab treatment completely reversed the levels of cytokines/chemokines, anti‐microbial peptides, or proliferation‐related molecules, such as CXCL8, CCL20, IL‐17A, IL‐17F, IL‐17C, keratin 16, IL‐36γ, DEFB4, or S100A7, in psoriasis lesional skin to the levels of non‐lesional skin." (PMID 38482898, 2024). "Among these, S100A7 (psoriasin) is particularly noteworthy for its role in psoriasis." (PMID 39769332, 2024). "Notably, S100A7 levels are elevated in lesional AD tissue, with immunostaining intensities comparable to those seen in psoriasis." (PMID 39769332, 2024). "Given that S100A7 is tightly associated with keratinocyte hyperproliferation in psoriasis, MSX2P1–miR−6731-5p biological regulation is a potential novel therapeutic target for treating psoriasis." (PMID 37310201, 2023). "Moreover, psoriasis-involved skin displays higher expression levels of transglutaminase and alteration in the interaction between S100A7 and transglutaminase." (PMID 37346040, 2023). "Results: we externally applied BZLF for skin lesions in an imiquimod-induced psoriasis mouse model and found that BZLF alleviated psoriasis-like skin lesions while inhibiting the expression of Ki67 and inflammatory factors (Il17a, Tnf-α, S100a7 and Cxcl1) in skin lesions." (PMID 36950008, 2023). "Many S100 proteins including S100A7/A8/A9/A12 are upregulated in psoriasis." (PMID 37049538, 2023). "Moreover, psoriasis-related cytokines and chemokines can upregulate S100A7 expression in normal and pathological conditions." (PMID 37346040, 2023). "Therefore, S100A7 widely affects the pathogenesis of psoriasis and the development of inflammatory reactions within the skin." (PMID 37891988, 2023). "Human S100A7 induces IL-1α expression in keratinocytes through RAGE-p38 MAPK-calpain-1 signaling, and psoriasis-associated cytokines, such as IL-17a, IL-22, and IL-36, may upregulate S100A7 expression in keratinocytes." (PMID 36613714, 2022). "In psoriasis, which is a chronic inflammation of the skin, S100A7 is overexpressed." (PMID 36032165, 2022). "Vitamin D has an inhibitory effect on keratinocyte proliferation; decreases psoriasin (a skin peptide, S100A7, whose levels are elevated in the skin of people with psoriasis); increases the synthesis of keratin, tranglutaminase, involucrin, loricrin, and filaggrin in the skin." (PMID 35010995, 2021). "HBD-2 and S100A7 are secreted from psoriatic keratinocytes and activate the innate immune system through various mechanisms to induce inflammation, which contributes to the pathogenesis of psoriasis." (PMID 34445513, 2021). "Human S100A7 is a critical player in the psoriatic maintenance phase, which may be considered as an additional and potential target molecule for psoriasis treatment." (PMID 28060905, 2017). "The inflammatory protein S100A7 (Psoriasin) was discovered as a marker of human psoriasis lesion." (PMID 25622979, 2015).